EGFR (epidermal growth factor receptor)
Diseases named in the same sentence as EGFR in open-access papers (continued):
Sharing a sentence is not in itself a finding about the gene and the disease.
cancer (continued). "It is possible, that the efficient formation of membrane EGFR/E-cadherin/catenin complexes in a high density is crucial for activation of MAPK signaling and cancer progression in head and neck epithelial cells." (PMID 24722213, 2014). "Other studies have demonstrated that the EGFR and PI3K/Akt pathways mediate MMP expression and cell invasion in patients with various cancers." (PMID 25147440, 2014). "Amplification of epidermal growth factor receptor (EGFR) signalling is a common event contributing to uncontrolled proliferation and survival in a wide range of cancers." (PMID 24970218, 2014). "This is due to activation of EGFR/HER2 and Src signaling pathways in these cancers, leading to formation of invadopodia, and increased rates of metastasis." (PMID 25547174, 2014). "Many studies have investigated the role of human epidermal growth factor receptor (EGFR, also known as HER1 or ErbB1) in cancer." (PMID 25401099, 2014). "In contrast to EGFR and ERBB2, the potency of ERBB3 as a therapeutic target in cancer has only recently been recognized." (PMID 24970817, 2014). "Recent findings evidenced a synergistic interaction between MET and other RTKs, like EGFR, vascular endothelial growth factor receptor (VEGFR) and insulin-like growth factor-1 receptor (IGF-1R), promoting cancer invasiveness and resistance to chemotherapy." (PMID 28548075, 2014). "Higher EGFR and TIMP1 were observed more frequently in the carcinomas of upper thoracic segment esophagus (P = 0.032; 0.00046)." (PMID 25337715, 2014). "We have previously published on the importance of epidermal growth factor receptor (EGFR/ErbB1) signalling, particularly in ErbB2 overexpressing DCIS and also the role for Notch signalling in regulating DCIS cancer stem/progenitor cells." (PMID 23457626, 2013). "The Epidermal Growth Factor Receptor (EGFR) is a membrane-bound receptor that has been shown to have a major role in the pathogenesis and progression of different cancers." (PMID 23782513, 2013). "Lapatinib is a dual tyrosine kinase inhibitor for EGFR and HER2 and is used to treat trastuzumab-resistant HER2 positive cancers." (PMID 23128605, 2013). "In Hec50 cells, estrogen signaling via GPER results in a metalloproteinase/EGFR-dependent activation of downstream kinase pathways, including PI3K and ERK, both important players in cancer cell survival and growth." (PMID 24379833, 2013). "Recently, therapies targeting epidermal growth factor receptor (EGFR) have exhibited excellent anticancer effects with mildly adverse effects and significantly enhanced cancer radiosensitivity in preclinical and clinical studies." (PMID 23976954, 2013). "It has been reported that ADAM17 contributes to cancer cell progression through activation of the EGFR/PI3K/Akt and EGFR/Ras/MAPK/Erk signaling pathways." (PMID 24843386, 2013). "Thus, IL-6 from cancer cells may play a central role in EGFR-TKI-induced interstitial pneumonia." (PMID 23592411, 2013). "Similar arguments can be made about other inhibitors to key molecular targets such as BRAF or EGFR, PARP, and COX-2, thereby emphasizing the importance of such molecules in gene-specific target cancer therapy." (PMID 24040001, 2013). "EGFR is known to be activated under hypoxia and EGF is a well-known growth factor involved in cancer progression." (PMID 23405166, 2013). "EGFR and β-catenin signaling are the only two major pathways that have been studied as potential PTPRK targets in few published cancer studies." (PMID 23696788, 2013).
cancer (continued). "The overexpression of epidermal growth factor receptor (EGFR) and HER2 can be observed in a variety of human malignancies and the roles of such overexpressions in cancer development, progression and aggressiveness have been widely recognized." (PMID 23426935, 2013). "In cancer cells, the extracellular domain of the EGFR binds to the EGF and the EGF pathway is activated; signaling is initiated to regulate the differentiation, survival, proliferation and migration of cancer cells." (PMID 23420529, 2013). "For instance, NICD1/CSL transcription complex has been reported to induce EGFR activity and this activation is abolished by NOTCH1 knockdown in other cancers." (PMID 24143218, 2013). "Studies on the epidermal growth factor receptor (EGFR) in chick embryo back skin, which proliferates rapidly in EGF-containing medium, highlight the importance of EGF for cell proliferation and cancer development." (PMID 24340049, 2013). "Activation of EGFR, PI3K/AKT, or MAPK leads to down regulation of apoptosis; therefore, induction of apoptosis is one of the most obvious targets for cancer treatment." (PMID 24124611, 2013). "EGFR-TKI effectively blocks the EGFR pathway via suppression of EGFR phosphorylation and can therefore inhibit the growth of cancer cells dramatically." (PMID 23592411, 2013). "This epidermal growth factor receptor (EGFR)-blocking antibody, which blocks angiogenesis, only induced phenotypic maturation of DCs upon their co-incubation with treated cancer cells." (PMID 24376443, 2013). "The mammalian target of rapamycin (mTOR), is a downstream conduit of EGFR and MET signaling, and is thus considered a therapeutically attractive target in the treatment of various types of cancers." (PMID 23690929, 2013). "Consistent with this prediction, increased expression of the cancer invasion-related genes matrix metalloproteinase (MMP)-1, MMP-2, epidermal growth factor receptor (EGFR) and cyclooxygenase 2 (COX-2) were detected in the CD44+ stem-like cells." (PMID 23833643, 2013). "Luciferase reporter assays demonstrated that miR-574-3p directly binds to the 3′ UTR of several target genes (such as RAC1, EGFR and EP300) that are components of ‘Pathways in cancer’." (PMID 23554959, 2013). "ABCG2 is known to mediate the efflux of gefitinib (Iressa®) from cancer cells, and its expression is regulated by NRF2 and the EGFR-tyrosine kinase cascade." (PMID 24040073, 2013). "It is overexpressed in several cancers, including approximately 40–80% of NSCLC, which made EGFR a popular target for new drug treatment exploration." (PMID 23407898, 2013). "Our in vitro studies show that DPDIM exerts apoptotic effect by negatively regulating the activity of EGFR and its downstream molecules like STAT3, AKT and ERK1/2 which are involved in the proliferation and survival of these cancer cells." (PMID 23555785, 2013). "Epidermal growth factor receptor (EGFR) is also central to the promotion of cell growth and has a role in the development of cancer." (PMID 23800048, 2013). "EGFR and HER2, have been among the most extensively studied for the therapy of cancer over the past twenty years and a wealth of drugs directed against them have been either already approved or are in advanced clinical development." (PMID 23890105, 2013). "As occurs in many human cancer cells, HT1080 cells also express epidermal growth factor receptor (EGFR)." (PMID 24130806, 2013). "Among them, the following well-known cancer genes were found: MET, CDK4, MDM4, EGFR and PIK3CA (amplifications), and CDKN2A, MLLT3, HRAS, CARS and NF1 (deletions)." (PMID 23408991, 2013). "Acute interstitial pneumonia is one of serious side effects of epidermal growth factor receptor (EGFR)-tyrosine kinase inhibitor (TKI) treatment, while it often has significant clinical benefit in cancer patients." (PMID 23592411, 2013). "Inhibition of EGFR and HER2 signaling is one strategy for treating trastuzumab-resistant HER2 positive cancers." (PMID 23128605, 2013).
cancer (continued). "Furthermore, our findings suggest that the inhibition of IL-6-STAT3 axis in patients treated with EGFR-TKI could be not only a therapeutic target for their cancers but also an option to prevent the development of acute interstitial pneumonia as an adverse effect." (PMID 23592411, 2013). "Together our data support a model in which loss of DOK2 impairs negative feedback on oncogenic signaling, leading to enhanced EGFR-RAS signaling and cancer." (PMID 24255704, 2013). "MiR-21 is positively regulated by EGFR in cancer cells as demonstrated by the finding that AG1478, an EGFR-TKI, blocked EGFR induction of miR-21." (PMID 24349829, 2013). "Similar to EGFR, overexpression and aberrant activation of VEGFR2 has also been reported in several cancer cells, including NSCLC." (PMID 24124611, 2013). "Specifically, constitutive activation of EGFR-Ras and PI3K signaling in Drosophila glial progenitor cells gives rise to proliferative, invasive neoplastic glia that create transplantable malignant tumors." (PMID 23459592, 2013). "The active vitamin D can induce the expression of C/EBPβ and prevent the proliferation of LIP epidermal growth factor receptor, thus reducing the occurrence of EGFR-driven related cancers." (PMID 24967240, 2013). "The epidermal growth factor receptor (EGFR) tyrosine kinase inhibitor gefitinib (ZD1839, Iressa) is approved for cancer treatment." (PMID 23748900, 2013). "EGFR inhibition can reduce the expression of the BRCA1 protein, thereby making the cancer cells vulnerable to PARP inhibition." (PMID 24244833, 2013). "Epidermal growth factor receptor (EGFR), which is a receptor tyrosine kinase (RTK), initiates multiple signaling pathways related to cancer progression, such as those involved in cell proliferation, migration/invasion and the cell cycle." (PMID 23520446, 2013). "Simultaneous targeting of epidermal growth factor receptor (EGFR) and Met in cancer therapy is under pre-clinical and clinical evaluation." (PMID 23812422, 2013). "EGFR and MAPK are other important nodes that are activated in cancer and mediate proliferative signals." (PMID 23658826, 2013). "For instance, re-sequencing of signal transduction genes such as EGFR, KRAS, BRAF etc. is increasingly important approach for personalizing cancer therapies." (PMID 23349847, 2013). "Despite a clear role for EGFR activation in the development of cancer, a disease with many similarities to SMC activation following vascular injury, the role of EGFR in vascular disease is poorly defined." (PMID 24132149, 2013). "In 2004, Klinger showed that an antibody against Lewis y blocks the signal pathway mediated by EGFR and inhibits activation of RAS and phosphorylation of MAPK, in turn, suppressing carcinoma cell proliferation." (PMID 23894390, 2013). "Transcript levels of growth factors and their receptors, such as VEGFA, MET, ESR1, EGFR, and HER2 were relatively undetectable in CTCs compared to cancer cell lines." (PMID 22586443, 2012). "In contrast to what is seen in Hela cells, Rab7 has recently been suggested to promote EGFR stability in A431 and MCF7 cancer cells by protecting EGFR from proteosomal degradation." (PMID 22558469, 2012). "Our study demonstrates for the first time that this drug combination efficiently eliminates HNSCC cancer cells by evoking expression of the pro-apoptotic protein BIM (B cell lymphoma 2 interacting mediator of cell death) and by downregulation of EGFR." (PMID 22289787, 2012). "Over expression of EGFR and altered EGF signaling are common features in a variety of human cancers." (PMID 23185433, 2012). "The combination of low dose cisplatin and low dose UV-C synergistically exerted anti-cancer effect by down-regulating RTK, such as EGFR and HER2." (PMID 22788833, 2012).
cancer (continued). "Both EGFR and HER2 have been successfully targeted for cancer therapeutics including small molecule kinase inhibitors (such as gefitinib, erlotinib, and lapatinib) and therapeutic monoclonal antibodies (such as cetuximab, panitumumab, and trastuzumab)." (PMID 23342251, 2012). "Proteins known to be involved in growth signals, thus leading to self-sufficiency in cancer cells, such as TGFBR1, EGFR, IGFR1R, GRB2, are in the ‘hubs’ of CGN." (PMID 23166660, 2012). "Since the EGFR and PIK3CA are among the most frequently activated oncogenes in cancer, we suggest that the specific anti-oxidant transcriptional program driven by these oncogenes protects and favours the selection of the cells carrying the mutated proteins." (PMID 22662165, 2012). "In this study, we report that an anti-HER2 monoclonal antibody (HER2Mab), which blocks HER2 dimerization with HER3, induces HER3 dimerization with EGFR in both low and high HER2 expressing cancer cells." (PMID 23342251, 2012). "Most of these regions have been validated to encompass or closely near to cancer related genes such as MDM2, MYC, EGFR, ERBB2, CCND1, ARNT." (PMID 23285074, 2012). "They include three out of six proteins approved by FDA in specific cancer diagnosis: PSA/KLK3, EGFR and AFP." (PMID 22761861, 2012). "A phase II study conducted by the European Organization for Research and Treatment of Cancer (EORTC) Soft Tissue and Sarcoma Group demonstrated that gefitinib treatment specifically targeting EGFR failed in SS patients." (PMID 22550415, 2012). "Here, we use the epidermal growth factor receptor (EGFR), fibroblast growth factor receptor (FGFR) and PI3K/AKT signaling pathways to illustrate Reactome annotation of cancer pathways." (PMID 24213504, 2012). "The most well-characterised receptors of this family are EGFR and HER2, which are both overexpressed in a number of cancer types, respectively." (PMID 22768204, 2012). "In successfully treated cancers, PI3K signalling is attenuated or even turned off by EGFR- or HER2-targeting (using antibodies or receptor kinase inhibitors)." (PMID 22240798, 2012). "Apart from transcription factors and apoptosis, emerging studies shed light on latent targets of curcumin against epidermal growth factor receptor (EGFR), microRNAs (miRNA), autophagy and cancer stem cell." (PMID 22489192, 2012). "The EGF receptor family consists of four members: ErbB1/EGFR/HER1, ErbB2/HER2/Neu, ErbB3/HER-3 and ErbB4/HER-4 that are important for cancer development." (PMID 23173670, 2012). "EGFRvIII, a constitutively active mutant form of EGFR, is common in HNSCC as well as in other cancers known to be highly aggressive." (PMID 22384257, 2012). "Aberrant expression and activation of EGFR and ERBB2 (HER2) have been successfully targeted for cancer therapeutics." (PMID 23342251, 2012). "The epithelial growth factor receptor (EGFR) family consists of four members, EGFR (HER1), ErbB2 (HER2), ErbB3 (HER3), and ErbB4 (HER4), and has been shown to play an important role in metastasis and tumorigenesis in many types of human cancers." (PMID 22479527, 2012). "However, cancer cells have developed mechanisms to activate EGFR indirectly through cross-talk with other signaling pathways, which, in turn, may limit the benefits of currently-approved EGFR-targeted biological therapies." (PMID 23119029, 2012). "A recent clinical study demonstrated a link between EGFR and ErbB2 inhibition and reduced CD44+/CD24low expression, the cancer stem cell marker in breast cancer." (PMID 22384257, 2012). "Indeed, activating KRAS, BRAF and PIK3CA mutations are able to bypass EGFR pharmacological inhibition, thereby resulting in a constitutive activation of the mitogen-activated protein kinase and AKT pathways, known to play a central role in cancer onset and progression." (PMID 22911782, 2012). "ERBB3 is a critical activator of PI3K signaling in EGFR (ERBB1)-, ERBB2 (HER2)-, and MET-addicted cancers." (PMID 23691449, 2012).
cancer (continued). "Recent studies have led to the recognition of the epidermal growth factor receptor HER3 as a key player in cancer, and consequently this receptor has gained increased interest as a target for cancer therapy." (PMID 22768204, 2012). "The EGF-NIR, rapidly saturated the EGFR in a focal CRC set-up, and was able to detect with high sensitivity 15–30% of EGFR expressing cells in a heterogeneous mixture of carcinoma/enterocyte cells in vitro." (PMID 23144978, 2012). "EGFR has been correlated with the proliferation activity, stage, ALI, carcinoma differentiation, invasiveness, and recurrence and it is proposed to play an important role in carcinogenesis and HCC progression." (PMID 23162604, 2012). "Therefore, inhibitors of EGFR — inhibiting EGFR's kinase activity by competing with its cognate ligands — may potentially constitute a new class of effective drugs in clinical use or cancer therapy." (PMID 21811593, 2011). "Altered expressions of EGFR and VEGF are early steps in the development of many cancers; therefore, these are appealing targets for early tumor detection by PID." (PMID 22214225, 2011). "The ErbB tyrosine kinase superfamily, comprising the epidermal growth factor receptor (EGFR; also known as ErbB1/HER1), ErbB2 (HER2/neu), ErbB3 (HER3) and ErbB4 (HER4), plays important roles in cancer development and progression." (PMID 21789172, 2011). "Recently, new small molecule-based therapeutics targeting EGFR, including erlotinib (Tarceva, OSI Pharmaceuticals), have proven useful in other cancers with upregulation of EGFR signaling." (PMID 21725138, 2011). "This oncogene dependency provides a basis for targeting activated oncogenes in treatment as exemplified by the success of imatinib and erlotinib in cancers that harbor BCL-ABL and EGFR alterations, respectively." (PMID 21931712, 2011). "One cancer drug target is the epidermal growth factor receptor (EGFR, also called ErbB1 and human epidermal growth factor receptor 1 (HER 1))." (PMID 22276062, 2011). "We have previously shown that EGFR, when tyrosine-phosphorylated, binds to GEP100/BRAG2 to activate Arf6, which induces cancer invasion and metastasis." (PMID 21966491, 2011). "Aftertreatment with TSA, the reduced EGFR expression was also seen in human skin(A431) and breast (MDA-MB468) cancer cells." (PMID 21464950, 2011). "The combination of an EGFR inhibitor, lapatinib or gefitinib, with SN38 achieved a greater suppression of cancer cell proliferation in all four cell lines tested than monotherapy with either agent alone." (PMID 21997136, 2011). "Accordingly, increased activity and overexpression of both EGFR and the MEK1/2 kinases has been observed in various human cancers." (PMID 21445343, 2011). "Our results indicate that E-cad is probably involved in regulation of both EGFR-ERK and EGFR-AKT pathways, resulting in SCCHN cancer cell proliferation." (PMID 21939503, 2011). "While JAK2 mutation is a common means to stimulate oncogenic STAT activity, perturbations in other signaling networks, such as those mediated by EGFR, IL-6/IL-6R or FLT3, can also contribute to activated STAT signaling in cancer cells." (PMID 21533169, 2011). "In cancers, HIF-1 participates in the activation of autocrine signaling pathways involving TGF-a/EGFR and EGF-2/IGF-1R, which promote cell survival and proliferation." (PMID 21492463, 2011). "Upregulation of EGFR and activation of downstream targets like ERK1/2 play a critical role in EMT, which in turn has been involved in cancer cell invasion and metastasis." (PMID 22188922, 2011). "However, it is also likely that immunohistochemistry evaluation of EGFR protein expression may not be accurate enough to detect loss of EGFR protein in cancer tissues, thus compromising data analysis and interpretation in this setting." (PMID 21559018, 2011).